IL10 (interleukin 10)
Diseases named in the same sentence as IL10 in open-access papers (continued):
Sharing a sentence is not in itself a finding about the gene and the disease.
periodontitis (continued). "The IL-10 gene polymorphism at position −597 seemed to be associated with severe generalized chronic periodontitis in a Turkish population." (PMID 35454140, 2022). "Consistently with it, IL-10- rs1800872 AA genotype and rs1800871 TT genotypes were associated with increased A. actinomycetemcomitans counts in periodontitis." (PMID 35122548, 2022). "The IBD activity was associated with significantly increased expression of IL-4, IL-10 and IL-21 in the gingival tissue of patients with periodontitis." (PMID 34501547, 2021). "IL-10 polymorphism is of high clinical relevance and a valuable marker to recognize patients who are at higher risk for periodontitis." (PMID 35046930, 2021). "Previous studies have investigated the pathogenesis of periodontitis and its association with the inflammatory cytokines IL-1β, IL-4, IL-6, IL-10, interferon-γ (IFN-γ), and TNF-α39." (PMID 34764408, 2021). "IL-10 592C>A A allele model had a strong relationship in the prevention of periodontitis risk with OR (95% CI), 1.21 (1.03–1.39)." (PMID 35046930, 2021). "IL-10 1082A>G A allele model also had a weak relationship with the periodontitis development with OR (95% CI), 1.04 (0.81–1.28)." (PMID 35046930, 2021). "Polymorphisms of IL-10 have been associated with those of tumor necrosis factor α IL-1α, IL-1β and IL-1RA in periodontitis." (PMID 34069916, 2021). "These roles were confirmed by experiments with IL-10-deficient mice that showed great susceptibility to P. gingivalis-induced periodontitis together with high pro-inflammatory phenotypes." (PMID 32397555, 2020). "IL10 is an anti-inflammatory cytokine, which plays a vital role in periodontal diseases; polymorphisms in the IL10 gene have been associated with periodontitis." (PMID 32867386, 2020). "Given that IL-10 can inhibit the matrix metalloproteinases and reduce the periodontal tissue destruction, recommended to reveal the possible relationship between IL-10 polymorphisms (− 1082, − 819, − 592) and chronic periodontitis." (PMID 30755190, 2019). "IL-1Ra and IL-8 concentrations were higher in those with medium or high risk (CRS II and CRS III, p < 0.001) of periodontitis, whereas IL-10 and TNF-α concentrations were lower when compared to those with low risk (CRS I)." (PMID 31817464, 2019). "Though in stage 3 periodontitis the severity of periodontitis correlates with bone loss, the presence of IL10 is reduced in such a situation." (PMID 31871458, 2019). "The [ATA] haplotype has been associated with decreased synthesis of IL-10 and is frequently associated with periodontitis." (PMID 30327689, 2018). "The association between interleukin-10- (IL-10-) 592 (-590, -597) C>A polymorphisms and susceptibility to chronic or aggressive periodontitis (CP or AgP) is conflicting." (PMID 30327689, 2018). "In the CP group, IL-10 AA genotypes were associated to risk of periodontitis development 7 times higher in comparison with IL-10 AC/CC genotype with a statistically significant risk coefficient (OR:7, 95%CI, 2.83-60.25, p<0.05)." (PMID 29489938, 2018). "For individual studies, odds ratio (OR) and its 95%confidence interval (CI) were calculated to assess the strength of association between IL10 polymorphisms (− 1082 A > G, -819C > T, − 592 A > C) and the risk of periodontitis." (PMID 30348144, 2018). "In conclusion, despite of the limitations of sample size, the results of this study suggest that the possible influence of IL-10 polymorphisms on the susceptibility to chronic periodontitis." (PMID 29899423, 2018). "Since that time, there have been another 12 studies reporting the association between IL-10-592 (-590, -597) C>A polymorphisms and periodontitis susceptibility, though the findings have been inconsistent." (PMID 30327689, 2018). "In conclusion, this study demonstrated that IL-10 -597 AA genotype appeared to be a risk factor for chronic periodontitis." (PMID 29489938, 2018).
periodontitis (continued). "As a result, we found that IL-10 AA genotypes were associated with chronic periodontitis and IL-10 AA genotype carriers showed lower IL-6/IL-10 levels in serum." (PMID 29489938, 2018). "The objective of the current review was to investigate the association between IL10 polymorphisms − 1082 A > G (rs1800896), -819C > T (rs1800871), − 592 A > C (rs1800872) and the risk of either chronic periodontitis or aggressive periodontitis." (PMID 30348144, 2018). "In this study, patients with the IL-10 AA genotype had a high susceptibility to chronic periodontitis." (PMID 29489938, 2018). "There are molecular epidemiological studies that assessed the association between IL10 and the risk of developing periodontitis." (PMID 30348144, 2018). "On the contrary, IFNgamma and IL10 had an opposite function to the pro-inflammatory ones, as higher levels of these mediators were associated with a reduced probability of having periodontitis." (PMID 28912468, 2017). "The relationship between IL-10 -592 C/A gene polymorphism and chronic periodontitis was suggested by two meta-analyses." (PMID 28624837, 2017). "We analyzed the effects of non-surgical perio-dontal therapy on the clinical parameters between SCP and NSCP to chronic periodontitis, according to the IL-6 -572 G/C, IL-10 -592 C/A polymorphisms as well as their combination." (PMID 28624837, 2017). "It is likely that IL-10 polymorphisms modulate the levels of protein and are associated with chronic periodontitis." (PMID 28348592, 2017). "The increased ratio IL-1β/IL-10 in gingival crevicular fluid can be associated with the progression of aggressive periodontitis." (PMID 28662142, 2017). "Many researchers have attempted to find useful biomarkers such as TNF-α, IL-10, IL-17, IL-12, and IL-1β in saliva that are associated with periodontitis to help predict or diagnose T2DM." (PMID 29109737, 2017). "Meta-analyses have also confirmed a positive association between IL-6, IL-10 gene polymorphisms and chronic periodontitis." (PMID 28624837, 2017). "Key words:According to MeSH documentation, chronic periodontitis, cytokines, genetic polymorphism, interleukin-10, periodontal disease." (PMID 25129246, 2014). "Given the fact that IL-10 can inhibit bone loss, the use of IL-10 will be an effective therapeutic method for periodontitis and other bone loss diseases." (PMID 24696846, 2014). "The levels of regulatory cytokine IL-10 in patients with periodontitis carrying the appropriate genotypes of IL-4 polymorphisms were also significantly increased, after stimulation with P. intermedia." (PMID 25530681, 2014). "IL-10 polymorphism has been associated with chronic periodontitis and our data are in accordance with other investigations showing that SNPs in the IL-10 gene are associated with an increased risk and progression of periodontitis." (PMID 24274085, 2013). "Our data show that the A allele of IL-10 is more frequent in patients with periodontitis than in CTR and is a genetic risk factor for the disease (OR = 2.364)." (PMID 24274085, 2013). "The C allele of Vascular Endothelial Growth Factor, A allele of Interleukin 10 and GG genotype of Tumor Necrosis Factor-α were individually associated with chronic periodontitis." (PMID 24274085, 2013). "IL-10 SNPs, located both in the promoter or exon regions of the gene, resulted associated with a lower risk of chronic periodontitis." (PMID 24274085, 2013). "Our findings are also in agreement with a recent report showing an IL-10 SNP association with chronic and aggressive periodontitis." (PMID 24274085, 2013). "The IL-10 -1082 polymorphism was evident in our results, displaying a lower frequency of the A/A genotype in periodontitis patients than the healthy controls (63% versus 92%)." (PMID 23046796, 2012). "The odds ratio for carriage of IL-10 allele (G/G and A/G genotypes combined compared with the A/A genotype) was 6.555 (95% CI: 3.232-13.265) in periodontitis patients." (PMID 23046796, 2012).
periodontitis (continued). "Reduced IL10–mediated regulation may favor prolonged inflammatory responses, as suggested by studies on periodontitis and periapical lesions that reported associations between low-producer IL10 genotypes and increased tissue breakdown." (PMID 41614937, 2026). "IL‐10‐deficient mice with periodontitis show increased IL‐17 expression and more severe bone loss." (PMID 41399014, 2025). "IL-10 is implicated in oral cavity diseases, including periodontitis and salivary gland disorders." (PMID 41289041, 2025). "Additionally, it is important to explore the interactions between IL-10 SNPs and other genetic, environmental, and lifestyle factors to develop a comprehensive risk profile for periodontitis." (PMID 39336814, 2024). "These IL-10 gene polymorphisms have been proposed as potential risk factors for periodontitis." (PMID 39336814, 2024). "Similarly, another study reported that IL-10 dampens an excessive IL-17-mediated pro-inflammatory cytokine circuit in Porphyromonas gingivalis–induced experimental murine periodontitis and ligature-induced alveolar bone-loss models." (PMID 39253090, 2024). "Therefore, this study aimed to determine the diagnostic accuracy of salivary levels of tissue destruction-associated biomarkers (IL-1β and IL-10) for differentiating periodontal health from periodontitis and stable from unstable periodontitis." (PMID 39445112, 2024). "Moreover, variants in the IL-10 promoter gene have been associated with a predisposition to chronic periodontitis." (PMID 39253090, 2024). "Widespread expression of the M2 macrophage’s IL-10 in inflamed periodontal tissue is linked to tissue healing, a reduction in periodontitis severity, and a reduction to inflammation (Lappin, MacLeod, Kerr, Mitchell and Kinane, 2001; Garlet, Martins, Fonseca, Ferreira and Silva, 2004; Garlet, 2010)." (PMID 38347915, 2024). "Indeed, in young adults, subjects with periodontitis were associated with a higher ratio of interleukin-1 beta and interleukin-10 levels compared to clinically healthy periodontium subjects." (PMID 39857870, 2024). "There were significant associations between the periodontitis group and IL-10 and IL-18 levels." (PMID 39080003, 2024). "We evaluated the influence of the IL-10 polymorphisms on the key parameters of periodontitis, including severe clinical attachment loss (CAL ≥ 5 mm) and the deepest periodontal pockets (PD > 7 mm), considering additional factors such as gender and tobacco smoking." (PMID 39336814, 2024). "Furthermore, meta-analyses have highlighted an association between the IL-10 −1082 single-nucleotide polymorphism (SNP), particularly the G-allele, and periodontitis in European and Latino populations." (PMID 39336814, 2024). "Meta-analyses have suggested a significant association between the rs1800872 polymorphism of the IL-10 gene and periodontitis, observed in both the dominant model (CA + AA vs. CC) and the allelic model (A allele vs. C allele) across Caucasian, Asian, and mixed populations." (PMID 39336814, 2024). "Variations in the IL-10 gene may affect an individual’s susceptibility to periodontitis by altering the efficacy of these regulatory mechanisms." (PMID 39336814, 2024). "Low expression of IL-10 is associated with the development of immunopathology in response to infection and an increased risk for the development of chronic inflammatory diseases such as periodontitis." (PMID 39253090, 2024). "In addition, IL-10 has been shown to dampen an IL-17-mediated periodontitis-associated inflammatory network by acting on the cells of innate immunity." (PMID 36983201, 2023). "IL-10 has been previously identified in the oral cavity, specifically in periodontal ligament cells and in gingival crevicular fluid, and decreased IL-10 levels are associated with the pathogenesis of periodontitis." (PMID 37508659, 2023).
periodontitis (continued). "The subgroup analysis by ethnicity revealed that the IL-10 −1082A > G polymorphism was significantly associated with periodontitis risk in Caucasians, IL-10 −819C > T polymorphism in mixed population, and IL-10 −592C > A polymorphism in both Asians and mixed populations." (PMID 35454140, 2022). "Thus, the aim of the present study was to evaluate salivary concentrations of IL-1β, IL-6, MMP-8, and IL-10 in healthy and periodontitis patients and to assess the association between these biomarkers levels and clinical parameters in a Moroccan population." (PMID 35368315, 2022). "Nonetheless, IL-6 and IL-10 polymorphisms are found to be potential risk factors for periodontitis." (PMID 35571048, 2022). "Moreover, the IL-10 −1082A > G, IL-10 −819C > T, and IL-10 −592C > A polymorphisms were associated with periodontitis risk by ethnicity." (PMID 35454140, 2022). "However, the IL-10 SNP (− 1081) has only been associated with patients who smoke or have a history of periodontitis." (PMID 35061134, 2022). "Indeed, Il10−/− mice demonstrated high susceptibility to bone loss induced by the periodontal pathogen P. gingivalis and ligature-induced periodontitis." (PMID 33562334, 2021). "IL-10 has also been associated with the development of periodontitis." (PMID 31973090, 2020). "On contrary, we found that serum levels of the anti-inflammatory mediator IL-10 were significantly lower after periodontal induction, thus, confirming that periodontitis may predispose to a systemic inflammatory state." (PMID 31583485, 2020). "In the CP group with severe phenotype, IL-10 ATA/GCC genotypes were associated with higher risk of either periodontitis development or bone decay in comparison with IL-10 ATA/ACC-ATA/ATA-ACC/ACC genotypes, with a statistically significant risk coefficient (OR: 7, 95%CI, 2.83–60.25, p < 0.05)." (PMID 32397555, 2020). "There is current evidence that the local induction of IL-10 competency of B10 cells could ameliorate both inflammation and bone loss in ligature-induced experimental periodontitis." (PMID 32604936, 2020). "Also, the gingival application of an optimized combination of CD40L, IL-21, anti-Tim1, which in vitro induces IL-10 production on B10 cells, inhibited bone loss in ligature-induced experimental periodontitis." (PMID 31379856, 2019). "The purpose of this study was to evaluate the effect of interleukin-10 (-597) gene polymorphism and genotype distributions on chronic periodontitis (CP) development and IL-6 and IL-10 levels in gingival crevicular fluid (GCF) and serum before and after non-surgical periodontal treatment." (PMID 29489938, 2018). "Therefore, in the present meta-analysis, we include a total of 18 studies to further identify the contributions of IL-10-592 (-590, -597) gene variations to periodontitis (CP/AgP) susceptibility in a larger number and range of patients." (PMID 30327689, 2018). "IL10 is a key regulatory cytokine involved in the suppression of inflammation and return to homeostatic state and extensive evidence links increased levels of IL10 with resistance to inflammatory bone loss in experimental periodontitis." (PMID 29882907, 2018). "In addition, IL-10 ATA/ATA genotype is associated with the subgingival quantity of A. actinomycetemcomitansi in subjects with chronic periodontitis." (PMID 29899423, 2018). "Investigating the association of the IL10 gene polymorphisms with periodontitis susceptibility may promote our understanding of its pathogenesis and explain individual differences in the risk." (PMID 30348144, 2018). "This study investigated the influences of IL-10 polymorphisms on the susceptibility to chronic periodontitis (CP) and aggressive periodontitis (AP), and their possible role in the quantity of subgingival bacteria Aggregatibacter Actinomycetemcomitans and Porphyromonas gingivalis." (PMID 29899423, 2018).
periodontitis (continued). "On the basis of these clinical data, IL-10 polymorphisms may influence the composition of the subgingival bacteria by regulating IL-10 levels, and then be responsible for susceptibility to periodontitis." (PMID 29899423, 2018). "We suggest that when patients are initially diagnosed with periodontitis clinically, testing for IL-10-592 (-590, -597) polymorphisms may be helpful in confirming diagnosis." (PMID 30327689, 2018). "However, the presence of periodontitis at baseline was associated with a fall in serum IL10 levels, and serum baseline P. gingivalis antibody levels were also associated with a fall in serum IL10 levels and an increase in serum TNFα levels." (PMID 26963387, 2016). "In conclusion, ovariectomy promotes alveolar bone resorption in rats with experimental periodontitis and the possible underlying mechanism may be due to the decreased IL-10 and increased IL-6, OPG, and RANKL in ovariectomized periodontal tissues." (PMID 24683547, 2014). "We expect that IL-10 protein therapy could be tested by examining bone loss in ligature-induced periodontitis and bone turnover in ovariectomized rats." (PMID 24696846, 2014). "It was shown that IL-10-deficient mice presented superior bone loss, accompanied by higher IL-17 and IL-17–mediated chemokine and cytokine transcript levels compared with control mice after induction of experimental ligature-induced periodontitis with P. gingivalis." (PMID 41289041, 2025). "However, genetic polymorphisms or epigenetic modifications that reduce IL-10 expression may increase susceptibility to both periodontitis and its systemic complications." (PMID 41155385, 2025). "In addition, Il-10 gene polymorphisms may be associated with a predisposition to chronic periodontitis development, which indicates cystatin C could contribute to the inflammatory process decrease by IL-10 production." (PMID 38708345, 2024). "Mice deficient in IL-10 exhibited greater bone loss, which was accompanied by elevated levels of IL-17 and IL-17-mediated chemokine and cytokine expression in both the Porphyromonas gingivalis-induced experimental murine periodontitis model and the ligature-induced alveolar bone loss model." (PMID 39253090, 2024). "AndIL-10 polymorphisms may modulate the host’s risk for periodontitis through various IL-10 levels." (PMID 29899423, 2018). "For this reason, IL-10 gene polymorphism might contribute to periodontitis development." (PMID 29489938, 2018). "The increased ALP activity and IL-10 in PDG indicate that diacerein mitigates periodontitis impact on alveolar bone in rat molars." (PMID 41751209, 2026). "Our data demonstrate that genetically engineered MSCs overexpressing IL10 are suitable for the management of periodontitis and provide new insights into periodontitis cell therapy." (PMID 41181974, 2025). "In periodontitis model, IL‐10‐MSCs treatment significantly increased the M2 phenotype of macrophages at the lesion site." (PMID 41181974, 2025). "IL-10 is thought to play a role in periodontitis by reducing the production of proinflammatory cytokines and stimulating the production of protective antibodies." (PMID 39964474, 2025). "IL-10 transcript levels were elevated in the gingiva of patients with periodontitis, and the IL-17/IL-10 ratio was increased in their gingival tissues." (PMID 41289041, 2025). "IL-10 has emerged as a promising therapeutic molecule for periodontitis due to its ability to down-regulate chronic inflammation-associated cytokines, such as IL-17." (PMID 41289041, 2025). "IL‐10 is a famous wide‐spectrum anti‐inflammatory factor that possesses crucial protective effects in numerous diseases such as periodontitis." (PMID 41181974, 2025). "In fact, obesity can impact serum concentrations of pro-inflammatory mediators [such as IL-6, CRP, TNF-α, resistin, and leptin] and anti-inflammatory mediators (Adiponectin and IL-10) in individuals with periodontitis." (PMID 40422620, 2025).